RN7SL288P (RNA, 7SL, cytoplasmic 288, pseudogene)
Gene: Miscellaneous RNA gene on chromosome 13 (46,169,458 to 46,169,748, reverse strand). Ensembl gene ENSG00000240767.
Homologues: Orthologues: chimpanzee Metazoa_SRP (99% identical), macaque Metazoa_SRP (94% identical). Paralogues in human: RN7SL1 (84% identical), RN7SL664P (84% identical), RN7SL2 (83% identical), RN7SL3 (83% identical), RN7SL597P (83% identical), RN7SL220P (82% identical), RN7SL566P (81% identical), RN7SL126P (81% identical), RN7SL397P (81% identical), RN7SL658P (81% identical), RN7SL296P (80% identical), RN7SL679P (80% identical), and 703 more.